NUDT18 (nudix hydrolase 18)
Description:
Mediates the hydrolysis of oxidized nucleoside diphosphate derivatives. Hydrolyzes 8-oxo-7,8-dihydroguanine (8-oxo-Gua)-containing deoxyribo- and ribonucleoside diphosphates to the monophosphates. Hydrolyzes 8-oxo-dGDP and 8-oxo-GDP with the same efficiencies. Also hydrolyzes 8-OH-dADP and 2-OH-dADP. Exhibited no or minimal hydrolysis activity against 8-oxo-dGTP, 8-oxo-GTP, dGTP, GTP, dGDP and GDP. Probably removes oxidized guanine nucleotides from both the DNA and RNA precursor pools. In vitro, it catalyzes the hydrolysis of isoprene pyrophosphates, including (2E)-geranyl diphosphate, isopentenyl diphosphate, (2E,6E)-farnesyl diphosphate and dimethylallyl diphosphate. It may therefore play a role in the control of cellular levels of these metabolites that are essential for multiple cellular processes, including isoprenoids synthesis and protein isoprenylation (Probable).
Synonyms: MTH3; FLJ22494
Tractability: PROTAC: ubiquitination databases record sites on it; its protein half-life has been measured.
Gene: Protein-coding gene on chromosome 8 (22,105,748 to 22,109,419, reverse strand). Ensembl gene ENSG00000275074.
Subcellular location (Human Protein Atlas): Nucleoplasm; Golgi apparatus
Pathways (Reactome):
Metabolism: Phosphate bond hydrolysis by NUDT proteins
Gene Ontology:
Molecular function: 8-hydroxy-dADP phosphatase activity; 8-oxo-dGDP phosphatase activity; 8-oxo-GDP phosphatase activity; farnesyl diphosphatase activity; isoprenoid diphosphate phosphatase activity; protein binding; hydrolase activity; nucleoside diphosphate phosphatase activity
Biological process: dADP catabolic process; dGDP catabolic process; GDP catabolic process; nucleobase-containing small molecule metabolic process
Cellular component: Golgi apparatus; nucleoplasm; cytosol
Genetic constraint (gnomAD): Loss-of-function variants: 26 observed, 21.83 expected, observed/expected ratio (o/e) 1.19, 90% interval 0.87 to 1.64. The synonymous counts are far from expectation, so gnomAD's model fits this gene poorly and the ratio says little. Missense variants: 450 observed, 389.29 expected, observed/expected ratio (o/e) 1.16, 90% interval 1.07 to 1.25. Synonymous variants: 220 observed, 175.14 expected, observed/expected ratio (o/e) 1.26, 90% interval 1.12 to 1.4.
Homologues: Orthologues: chimpanzee NUDT18 (100% identical), macaque NUDT18 (96% identical), pig NUDT18 (89% identical), dog NUDT18 (88% identical), rat Nudt18 (82% identical), guinea pig NUDT18 (82% identical), mouse Nudt18 (81% identical), zebrafish nudt18 (43% identical), tropical clawed frog nudt18 (43% identical), Drosophila melanogaster CG10898 (35% identical), Caenorhabditis elegans ndx-1 (28% identical). Paralogues in human: NUDT17 (19% identical), NUDT1 (13% identical), NUDT12 (11% identical).
Diseases named in the same sentence as NUDT18 in open-access papers:
NUDT18 is named in the same sentence as 6 diseases in open-access papers, as found by Europe PMC text mining. Sharing a sentence is not in itself a finding about the gene and the disease. The quoted sentences say what the papers report.
leukemia (1 paper, 2022). A malignant (clonal) hematologic disorder, involving hematopoietic stem cells and characterized by the presence of primitive or atypical myeloid or lymphoid cells in the bone marrow and the blood. "To validate the function of SETD1A target genes (COX15, HMBS, UROS, RRNAD1, NUDT18, GSTZ1, HINT2, and COX18) in leukemia cells, we performed a CRISPR-based competitive cell proliferation assay in doxycycline-inducible Cas9-expressing MOLM-13 leukemia cells." (PMID 36450243, 2022).
liver cancer (1 paper, 2023). An epithelial or non-epithelial malignant neoplasm that arises from the liver. "Furthermore, using a whole-genome CRISPR-Cas9 screening approach, we identified the Nudix (nucleoside diphosphate–linked moiety X) hydrolases NUDT17 and NUDT18 as synthetic lethal paralogs, suggesting that NUDT17 may be targetable in liver cancer cells with chr8pLOH." (PMID 38134284, 2023).
cancer (2 papers, 2017 to 2023). A tumor composed of atypical neoplastic, often pleomorphic cells that invade other tissues. "Similar to NUDT18, NUDT1 is a major cleanser of the cytosolic pool of oxidized nucleotides and has been studied as a potential target in several cancer entities." (PMID 38134284, 2023).
tumor (2 papers, 2017 to 2023). "This confirmed that the NUDT17 dependency in chr8p-deleted tumor cells is caused by reduced NUDT18 expression." (PMID 38134284, 2023). "In conclusion, we propose that NUDT18 reduction by chr8pLOH sensitizes these tumor cells for NUDT17 targeting." (PMID 38134284, 2023). "We performed in-depth validation of our CRISPR-Cas9 screen in independent isogenic cell clones of three different cell lines that clearly validated that lack of the NUDT18 paralog in chr8pLOH tumor cells sensitized them to NUDT17 ablation." (PMID 38134284, 2023).
NUDT18 also shares sentences with these, for which no sentence is quoted: breast carcinoma (1 paper); colorectal cancer (1).